ENPP2 (ectonucleotide pyrophosphatase/phosphodiesterase 2)
Diseases named in the same sentence as ENPP2 in open-access papers (continued):
Sharing a sentence is not in itself a finding about the gene and the disease.
COVID-19 (6 papers, 2021 to 2023). A disease caused by infection with severe acute respiratory syndrome coronavirus 2. "As viral infections have been reported to stimulate ENPP2 mRNA expression, and to examine if CoV-2 infection has similar effects, we first quantified ENPP2 mRNA levels with Q-RT-PCR in nasopharyngeal swab samples." (PMID 34576169, 2021). "Therefore, CoV-2 infection stimulates ENPP2 mRNA expression in the respiratory epithelial or immune cells that compose the nasopharyngeal swab samples." (PMID 34576169, 2021). "Tmem176B has also been associated with an immature state of dendritic cells, suggesting that ENPP2 expression from COVID-19 pDCs, via LPA, delays their maturation." (PMID 34576169, 2021). "Confined by the limited numbers of lung pDCs, as well as the detected genes per cell and the relatively low expression levels of ENPP2, the analysis indicated a statistically significant overexpression of ENPP2 in COVID-19 circulating pDCs." (PMID 34576169, 2021). "ENPP2 mRNA expression was found upregulated in circulating pDCs, and lung DCs from COVID-19 patients in comparison to cells from healthy controls." (PMID 34576169, 2021). "scRNAseq analysis of BALF cells from COVID-19 patients indicated a predominance of macrophages, where ENPP2 mRNA expression was detected in monocyte-derived alveolar macrophages (Mo-AMs), that have been shown to drive the development of BLM-induced pulmonary fibrosis in mice." (PMID 34671341, 2021). "The hypothesis is further supported from the genes that have been discovered, pending validation, to be increased in COVID-19 DCs, possibly regulated by ENPP2." (PMID 34576169, 2021). "Moreover, large scale analysis of multiple single cell RNA sequencing datasets revealed the expression landscape of ENPP2 in COVID-19 and further suggested a role for ATX in the homeostasis of dendritic cells, which exhibit both numerical and functional deficits in COVID-19." (PMID 34576169, 2021). "Finally, and to gain mechanistic insights into the possible role of ATX in DC homeostasis upon COVID-19, we first analyzed differential gene expression in COVID-19 DCs (as pDCs were too few), from the only COVID-19 lung dataset allowing such analysis, as well as in ENPP2-expressing (ENPP2+) DCs." (PMID 34576169, 2021). "There is a significant reduction in the expression of ENPP1, ENPP2, ENPP3, and NT5E in the blood of patients with severe COVID-19 when compared to HDs and a lower expression of ENPP2 and ENPP3 when compared to mild hospitalized cases." (PMID 36248842, 2022). "Herein, we detected the gene expression of ENPP1, ENPP2, ENPP3, ENTPD1 (CD39), ENTPD5, and NT5E (CD73) in the whole blood of COVID-19 patients." (PMID 36248842, 2022). "Here, increased ENPP2 mRNA levels were detected in immune cells from nasopharyngeal swab samples of COVID-19 patients, and increased ATX serum levels were found in severe COVID-19 patients." (PMID 34576169, 2021). "Interestingly, ENPP2 mRNA expression was mainly detected in pDCs among all PBMCs and BALF cells in COVID-19." (PMID 34576169, 2021). "A significant increase was found in ENPP2 mRNA expression in mild and severe COVID-19 patients, as compared to non-infected subjects." (PMID 34576169, 2021). "Several inflammatory mediators, such as ENPP2, C5, FASLG, VWF, and CSF1, additionally presented a more robust correlation with the core inflammatory networks in the severe group, and these factors were reported as independent significant indicators of severe COVID-19 in previous studies." (PMID 36776879, 2023).
lung cancer (6 papers, 2016 to 2022). A malignant neoplasm involving the lung. "ENPP2 is a gene that encodes autotaxin, which has been verified to be related to the growth and metastasis of melanoma tumor and stage I nonsmall cell lung cancer (NSCLC)." (PMID 32953885, 2020). "It has to be noted that in our previous work, ENPP2 hypermethylation in lung cancer was correlated with advanced cancer stage." (PMID 35409077, 2022). "Increased methylation of promoter and first exon cytosine-guanine dinucleotides(CGs) and respective decreased ENPP2 mRNA expression were found in prostate and lung cancers and were correlated to poor prognostic parameters." (PMID 35409077, 2022). "If to consider that ENPP2 (also known as LysoPLD or ATX) encoding autotaxin is not expressed by A549 cells in the herein EMT model (gene expression data), primarily the increased intracellular LPA pool might have functional consequences contributing to EMT in lung cancer cells." (PMID 26967245, 2016).
ovarian carcinoma (6 papers, 2013 to 2023). A malignant neoplasm originating from the surface ovarian epithelium. "Five of the 10 most down-regulated genes, Aldh1a2, Enpp2, Lgfbp5, Thbd, and Uchl1, have been previously implicated in ovarian cancer." (PMID 24672774, 2014). "Finally, it was proposed that induction of ENPP2 expression by VEGF was associated with an aggressive phenotype in ovarian cancer via a positive feedback loop." (PMID 36358855, 2022). "The gene ectonucleotide, pyrophosphatase/phosphodiesterase 2 (ENPP2), which encodes ATX, was identified as a potential gene causing platinum-resistance in ovarian cancer." (PMID 23574936, 2013). "Moreover, the ovarian cancer patient profiles of the GEPIA dataset showed a significant positive correlation of ATX (ENPP2) expression with DDR2 (DDR2) expression (r = 0.49, p = 3.1 × 10−32)." (PMID 34065317, 2021).
pulmonary fibrosis (6 papers, 2014 to 2025). Chronic progressive interstitial lung disorder characterized by the replacement of the lung tissue by connective tissue, leading to progressive dyspnea, respiratory failure, or right heart failure. "Pharmacological inhibition of ENPP2 signalling to treat pulmonary fibrosis reached phase 3 clinical trials (ClinicalTrials.gov Identifier: NCT03711162), although there are no studies published on tendon." (PMID 37314623, 2024). "The conditional deletion of ENPP2 in both pulmonary cell compartments diminishes lung fibrosis, implicating ATX in the pathogenesis of the disease." (PMID 37569902, 2023). "Elevated levels of Enpp2 have been observed in patients with asthma and pulmonary fibrosis." (PMID 40787440, 2025). "Conditional deletion of ENPP2 in bronchial epithelial cells and macrophages reduced ATX levels in BAL fluid and disease severity confirming a pathophysiological role for ATX in lung fibrosis." (PMID 32549377, 2020).
neuroblastoma (5 papers, 2018 to 2023). Neuroblastoma (NB) is the most common solid, extracranial childhood tumor. "AP-1 and SP seem to act on the ENPP2 promoter affecting its transcription in human neuroblastoma cell lines, whereas v-jun and c-jun also seem to hold a role." (PMID 36358855, 2022). "Curcumin also inhibits transcriptional activation of the motility, angiogenesis, and metastasis-stimulating factor autotaxin (ENPP2) in human neuroblastomas where the MYC gene paralogue MYCN is amplified." (PMID 33937075, 2021). "Interestingly, SP was found to regulate ENPP2 transcription in neuroblastoma cells by activating a CRE/AP-1-like element at position −142 to −149 and a GAbox at position −227 to −235 near the TSS of ENPP2." (PMID 34769391, 2021).
pancreatic cancer (5 papers, 2012 to 2024). "ENPP2 was less expressed in pancreatic cancer tumor tissues compared to normal tissues, suggesting that the decrease of bM2-like TAMs may be pathological." (PMID 39507421, 2024). "Compared to normal pancreatic tissue, pancreatic tumor tissue showed lower ENPP2 expression." (PMID 39507421, 2024). "Although a high expression of the ATX gene (ENPP2) correlates with a poor outcome in several types of cancer (such as B-cell lymphomas, renal cell carcinomas, liver or pancreatic cancers), it is now well established that the tumor microenvironment is an essential source of ATX." (PMID 31906151, 2019). "ENPP2 encodes autotaxin (ATX), an intracellular and excreted lysophosphatase that has been associated with development of aggressive cancer types, including pancreatic cancer." (PMID 22952646, 2012). "Additionally, the analysis of the publicly available microarray dataset GSE71729 confirmed a positive correlation between CCN1 and ENPP2, as well as TGFB1 expression in pancreatic cancer patients." (PMID 39273316, 2024).
liver cancer (4 papers, 2020 to 2025). An epithelial or non-epithelial malignant neoplasm that arises from the liver. "Lung, prostate and liver cancer presented a greater number of Promoter Associated (PA) DMCs for ENPP2 and were further pursued using large datasets retrieved from The Cancer Genome Atlas (TCGA), which allowed DMC correlation to clinicopathological parameters and gene expression." (PMID 34769391, 2021). "Several studies have highlighted the role of Enpp2 in cancer biology, where it affects the migration of liver cancer cells by producing LPA." (PMID 40787440, 2025). "Prior research has demonstrated the potential of ENPP2 as a prognostic biomarker in various cancers, including breast and liver cancer." (PMID 39731014, 2024).
prostate carcinoma (4 papers, 2012 to 2026). A carcinoma that arises from epithelial cells of the prostate gland. "In order to study any relation of ENPP2 methylation to cancer aggressiveness, we compared cell lines from hepatocellular and prostate cancer presenting a more (SKHEP1 and PC3 respectively) or less (HEPG2 and LNCAP respectively) invasive phenotype, using the GSE71627 study dataset." (PMID 34769391, 2021). "Among them, Fatty Acid Synthase (FASN) exhibited the best diagnostic performance in the TCGA validation cohort (AUC = 0.800), outperforming PTGS2 (0.783), ENPP2 (0.621), and CHRM1 (0.605), and was significantly overexpressed in prostate cancer tissues (|log2FC| > 1, adjusted P < 0.05)." (PMID 42228706, 2026).
Alzheimer disease (3 papers, 2015 to 2025). A progressive, neurodegenerative disease characterized by loss of function and death of nerve cells in several areas of the brain leading to loss of cognitive function such as memory and language. "Enpp2 is a target in Alzheimer’s disease (AD) known to induce GPCR signaling and mediate inflammation." (PMID 40178780, 2025).
breast tumor (3 papers, 2011 to 2023). "The bioinformatics analysis in human breast tumors demonstrated that ENPP2 is significantly correlated with cytokine signaling, leukocyte activation, inflammation, and immune response, suggesting that ENPP2 is associated with the chronic inflammation milieu in the breast tumor microenvironment." (PMID 37296899, 2023). "ENPP2 expression in human breast tumors showed a positive correlation with leukocyte activation involved in immune response, which is probably associated with the chronic inflammation milieu in the tumor microenvironment." (PMID 37296899, 2023). "Especially, ENPP2 was significantly correlated with “IL-6 cytokine receptor ligand interactions”, “LIF signaling 1 up”, “TGFβ receptor signaling” and “prolactin signaling pathway” in human breast tumors." (PMID 37296899, 2023). "By using gene expression profiling of primary breast tumors either expressing or lacking pStat3 protein, we identified a number of potential Stat3 target genes which may be involved in metastasis including ENPP2 (ATX)." (PMID 22140473, 2011).
colitis (3 papers, 2019 to 2023). Inflammation of the colon. "Consistently, deletion of Enpp2 gene decreased disease severity in both acute and chronic colitis induced by DSS with significant decreases in mucosal damage and inflammation." (PMID 31323936, 2019). "Lpar1 and Enpp2 gene expression were reduced in the mouse during the acute phase of dinitrobenzenesulfonic acid–induced (DNBS-induced) colitis, supporting a possible role for altered glial LPAR1 signaling in the pathogenesis of dysmotility following an inflammatory insult." (PMID 35166239, 2022). "In accordance with this, the reductions in Lpar1 and Enpp2 gene expression observed following acute colitis may constitute an early perturbation that, if sustained, lead to the histopathological changes seen in patients with CIPO." (PMID 35166239, 2022).
endometrial carcinoma (3 papers, 2021 to 2025). A malignant tumor arising from the epithelium that lines the cavity of the uterine body. "The identification of virulence genes for PCOS-associated endometrial carcinoma was also analyzed by AI algorithms LASSO, SVM, and the topological matrix, indicating both NAA15 linked to sedentary behavior and ENPP2 in hormonal response within PCOS were the novel biomarker for endometrial carcinoma." (PMID 40549330, 2025).
Hepatic steatosis (3 papers, 2019 to 2024). Steatosis is a term used to denote lipid accumulation within hepatocytes. "Surprisingly, both models of Enpp2- deficiency exhibited marked protection from high fat diet-induced hepatic steatosis." (PMID 30730895, 2019). "The downregulated ENPP2 gene is significantly enriched in BP, MF, and lipid metabolism-related pathways, and it has been shown that the lack of ENPP2 has a significant protective effect on hepatic steatosis, suggesting a possible role of ENPP2 gene in the metabolism of milk lipids." (PMID 35186023, 2022).
lung adenocarcinoma (3 papers, 2021 to 2023). A carcinoma that arises from the lung and is characterized by the presence of malignant glandular epithelial cells. "In prostate and lung adenocarcinomas, increased methylation of PA CGs was correlated to decreased ENPP2 mRNA expression and to poor prognosis parameters." (PMID 34769391, 2021). "We found that an inflammatory signature and cytolytic T cell score correlate with increasing ENPP2 expression in human lung adenocarcinoma patients, which is in line with findings in the literature that inflammatory cytokines like IL-1β, TNF-α, and IFN-γ can promote ATX expression." (PMID 37655662, 2023).
systemic lupus erythematosus (3 papers, 2021 to 2023). An autoimmune multi-organ disease typically associated with vasculopathy and autoantibody production. "Genetic polymorphisms of the ENPP2 gene, which encodes autotaxin, are reportedly involved in the disease activity of systemic lupus erythematosus, an autoimmune disease." (PMID 37108150, 2023).
thyroid cancer (3 papers, 2018 to 2022). "On the contrary, decreased ATX activity was caused by the cytokines IL-1β, TGF-β and IL-4 in thyroid carcinoma UTC-1736 cells, while IL-6 enhanced ENPP2 expression." (PMID 36358855, 2022).
viral infections (3 papers, 2021). "It has been reported that virus infection induces ectonucleotide pyrophosphatase-phosphodiesterase 2 (ENPP2) expression, the latter participates in tumor progression." (PMID 34805271, 2021). "Increased ENPP2 mRNA expression was detected in nasopharyngeal swabs from COVID-19 patients, likely from immune cells, suggesting that ATX/LPA might stimulate viral infections, that could include SARS-CoV-2." (PMID 34671341, 2021).
Arthritis (2 papers, 2014 to 2019). Inflammation of a joint. "Also, overexpression of ENPP2 has been documented during arthritis and the production of LPA by ENPP2/ATX plays a role in the development of cardiovascular disorders." (PMID 31251802, 2019). "In addition, symptoms of collagen-induced arthritis were attenuated in mice with conditional ATX/ENPP2 gene deletions, which suggested an involvement of ATX/ENPP2 in chronic inflammation." (PMID 24747415, 2014).
dyslipidemia (2 papers, 2020 to 2023).
invasive breast carcinoma (2 papers, 2018 to 2022). A carcinoma that infiltrates the breast parenchyma. "In addition, ENPP2 is one of 11 genes spanning the 8q12.1-q24.22 genomic region found to be differentially methylated and expressed in invasive breast carcinomas harboring the 8p11-p12 amplicon by integrative analysis." (PMID 35409077, 2022).
Nephroblastoma (2 papers, 2011). An embryonal neoplasm characterized by the presence of epithelial, mesenchymal, and blastema components. "Rs6993464 and six other SNPs with meta-analysis p-values < 1E-04 lie between the genes NOV (nephroblastoma overexpressed gene) and ENPP2 (ectonucleotide pyrophosphatase/phosphodiesterase 2)." (PMID 22142333, 2011).
Pulmonary hemorrhage (2 papers, 2021). Pulmonary hemorrhage is a bleeding within the lungs. "In adult mice, in studies unraveling the molecular mechanisms of SARS-CoV and MERS-CoV pathogenesis in the Collaborative Cross mice, Enpp2, the gene encoding ATX, has been reported to be a high priority candidate gene for pulmonary hemorrhage." (PMID 34671341, 2021). "In adult mice, ENPP2 has been discovered as a high priority candidate gene for pulmonary hemorrhage upon SARS/MERS-CoV infection, while vascular leak has been suggested to be among the main pathological effects of ATX/LPA in pulmonary pathophysiology and fibrosis in mice." (PMID 34576169, 2021).
Anxiety (1 paper, 2022). Intense feelings of nervousness, tension, or panic often arise in response to interpersonal stresses. "Additional upregulated genes included Enpp2, Atp1a2, Apoe and Slc1a3, which play a role in psychiatric conditions often related to withdrawal, such as anxiety and depression." (PMID 36534642, 2022).
astrocytomas (1 paper, 2021). "Therefore, we constructed Kaplan–Meier graphs using TCGA data for astrocytoma grades II, III and IV with low and high expression of LPAR1, LPAR3 and ENPP2." (PMID 33916643, 2021).
biliary atresia (1 paper, 2021). A rare, biliary tract disease characterized by progressive obliterative cholangiopathy of the intra- and extrahepatic bile ducts, occurring in the embryonic/ perinatal period, leading to severe and persistent neonatal jaundice and acholic stool. "A study in Biliary Atresia (BA) showed hypomethylation at four CpGs of ENPP2 promoter in the blood and liver of BA patients in relation to normal tissue and was correlated to increased ATX expression." (PMID 34769391, 2021).
coronary atherosclerosis (1 paper, 2024). Atherosclerosis of the coronary vasculature. "ENPP2 has been documented to promote coronary atherosclerosis by mediating LDL production through the generation of LPA 20:4, 16:0, and 18:1 and by inducing CXCL1 expression." (PMID 39731014, 2024).
fibrosis (1 paper, 2023). the formation of excess fibrous connective tissue in an organ or tissue in a reparative or reactive process. "The pyridine and pyrimidine derivative 1 drugs that target ENPP2 are used for treating fibrosis." (PMID 37209815, 2023).
follicular lymphoma (1 paper, 2014). Follicular lymphoma is a form of non-Hodgkin lymphoma characterized by a proliferation of B cells whose nodular structure of follicular architecture is preserved. "Serum ATX/ENPP2 levels are increased in patients with follicular lymphoma and in patients with intrahepatic cholestasis of pregnancy (ICP), suggesting that the LPA produced by ATX/ENPP2 may affect the pathology of these diseases." (PMID 24747415, 2014).
glaucoma (1 paper, 2021). Increased pressure in the eyeball due to obstruction of the outflow of aqueous humor. "Among the identified proteins significantly altered in glaucoma, eight were further studied using semi-targeted or targeted approaches, showing higher levels of ALB, APOC3, CysC, TIMP2, A2M, PGTDS, and ENPP2, and lower levels of SOD1, in POAG patients compared to control subjects." (PMID 34439995, 2021).
Hodgkins lymphoma (1 paper, 2021). A heterogeneous group of malignant lymphoid neoplasms of B-cell origin characterized histologically by the presence of Hodgkin and Reed-Sternberg (HRS) cells in the vast majority of cases. "Besides, in Hodgkin lymphoma, high levels of ENPP2 are strongly positivity associated with Epstein-Barr virus (EBV), EBV infection results in the induction of ENPP2 and leads to the enhanced growth and survival of Hodgkin lymphoma cells via the ENPP2/LPA axis." (PMID 34805271, 2021).